CXCL9 (C-X-C motif chemokine ligand 9)
Diseases named in the same sentence as CXCL9 in open-access papers (continued):
Sharing a sentence is not in itself a finding about the gene and the disease.
cancer (continued). "In conclusion, the findings highlight the clinical significance of M1 macrophage and CXCL9 as potential biomarkers for patient stratification and indicate the potential importance of RNA modification processes in impacting cancer immunotherapy response." (PMID 38434763, 2024). "Interferon gamma stimulates CXCL9 production by monocytes, endothelial cells, fibroblasts and cancer cells leading to increased chemotaxis and infiltration of the TME." (PMID 39080202, 2024). "A recent landmark pan-cancer metadata analysis identified CXCL9 expression as one of the strongest predictors of response to ICB in cancer patients." (PMID 38518770, 2024). "In view of the promising clinical applications of CXCL9, recent clinical studies have focused on its role in diseases such as COVID-19, autoimmune diseases, and cancer." (PMID 37644593, 2023). "Data collated and analysed from more than 1000 patients with different types of cancers treated with ICBT showed that intratumoural CXCL9 expression strongly correlated with ICBT response." (PMID 37503572, 2023). "In other solid tumors (e.g., ovarian or breast), CXCL9 is a favorable prognostic biomarker that indicates that the cancer will respond to immune checkpoint inhibitor therapy and is associated with longer survival in some cases." (PMID 37048724, 2023). "Similar to findings in vitro, significantly higher levels of Cxcl9/10/11 were observed in cancer cells isolated from MC1R-depleted tumors relative to control tumors." (PMID 37714844, 2023). "Of those, only T-cell-inflamed GEP, CD8A and CXCL9 expression showed significant predictive power across all cancer types." (PMID 37277866, 2023). "The inhibition of residual cancer growth mediated by nanosecond pulsed electric field ablation was dependent on CXCL9 axis." (PMID 37046739, 2023). "While previous studies have revealed that oncogenic GNAS mutants promote hyperplastic growth and tumorigenesis, our study demonstrates that they also promote immune evasion by repressing CXCL9/10/11 across human cancers." (PMID 37714844, 2023). "Other SASP chemokines such as CXCL9/10 that bind to CXCR3 and are associated with T cell recruitment and “hot” TMEs in other cancer settings are necessary for CD8+ T cell recruitment into PDAC following therapy-induced senescence." (PMID 37142692, 2023). "We found that CXCL9 protein levels were remarkably upregulated in miR-155–overexpressing cancer cells in the tumors and in cell culture as well as in miR-155–overexpressing cell culture medium and EO771-Bic TIF." (PMID 35925680, 2022). "The results revealed that CD45 was positively correlated with the expression levels of genes characteristic of exhausted T cells across cancers, such as CXCL9, IL10, CD28, IDO1 and CCR4." (PMID 36061172, 2022). "miR-1269a can regulate the occurrence and development of cancer by targeting downstream genes (CXCL9, SOX6, FOXO1, ATRX, RASSF9, SMAD7, HOXD10, and VASH1)." (PMID 35252180, 2022). "While the CXCL9/10/11/CXCR3 axis is more generally associated with antitumorigenesis, studies of its participation in cancer growth and metastasis have been published." (PMID 36164329, 2022). "This suggests that the upregulation of CXCL9, CXCL10 and CXCL11 is a common event in the cancers with viral or bacterial association." (PMID 35433690, 2022). "Similar to the pan-cancer analysis, LRP2 mutations had high TMB, MSI and immune cell infiltration in EC and also leaded to high expression of immune-related genes, such as CXCL9, CXCR6, CXCL13, ICOS and immune checkpoint genes (CTLA4 and LAG3)." (PMID 35834061, 2022). "CXCL9 positivity was mainly identified in cancer cells and myeloid cells, especially macrophages and dendritic cells." (PMID 35389889, 2022). "Although TFR1-positive cancer cells can be killed by H-ferritin drug nanocarrier when treated with IFN-γ, TFR1-deficient cells can upregulate the expression of PD-L1, CXCL9, and CXCL10 to promote immune escape." (PMID 36082181, 2022).
cancer (continued). "It is known that the chemokine CXCL9 interacts with the CXCR3 receptor to modulate CTL recruitment in human cancers." (PMID 36566226, 2022). "Especially the high expression of genes encoding CX3CL1, CXCL9 and CXCL10 has been found in carcinomas highly infiltrated by effector TCs, particularly TH1, which show higher overall and disease-free survival." (PMID 35954497, 2022). "CCL5, CXCL9, CXCL13, CXCL10, and CXCL11 were also among the top chemokine genes associated with the gene expression-based immune scores across multiple cancer types." (PMID 34030676, 2021). "For the multivariate Cox model for cancer-specific survival, CXCL9 showed significant results and CXCL11 showed a trend toward significance as independent prognosticators after controlling for the same covariates." (PMID 34501934, 2021). "The two key open-end questions are which human cancer to treat, and which of them CXCL9 would be favored over CXCL10, and when CXCL10 would be used as a lead molecule over CXCL9?" (PMID 34944943, 2021). "In particular, CXCL9 showed the most significant results as an independent prognosticator both for overall survival and for cancer-specific survival." (PMID 34501934, 2021). "It was found that CXCL9 and 10 were essentially enriched in mononuclear/macrophage subsets among the three cancers." (PMID 34439306, 2021). "The gene expression analysis using the Oncomine database showed that the mRNA levels of CXCL9 were significantly higher in BC than in normal tissues across an array of datasets in multiple cancer types." (PMID 34527583, 2021). "We used the TISCH database to analyze the distribution of CXCL9, 10, and 13 cells in each subgroup of three types of cancer." (PMID 34439306, 2021). "The expression levels of six chemokine genes (CCL5, CXCL9, CXCL13, CXCL10, CXCL11, and CCL19) were significantly associated with the image-based immune scores across all 13 tested cancer types." (PMID 34030676, 2021). "The results suggested that CXCL9 is one of the most correlations of abundant of immune cell infiltration than other ten innate immune prognostic biomarkers in multiple cancer types." (PMID 35052427, 2021). "Another previous study revealed a close association between the CXCL9 and CCL5 expressions in OV and other cancers." (PMID 33869044, 2021). "ATM and its downstream molecule Chk2 are the primary kinases responsible for G1/S phase arrest of the cell cycle, and S-phase-specific DNA damage has been reported to activate the immune response including induction of CXCL9, -10 expression in cancer cells." (PMID 34413454, 2021). "For example, the median cluster has lower expression of CXCL9 and CXCL10, which have been shown to be associated with TIL infiltration in human cancers and draw dendritic cells (DC) and CD8+ T cells 39-41." (PMID 33403028, 2021). "Based on the signaling pathway and immune evasion mechanism, the expression of the up-regulated CXCL9/10/11-CXCR3 gene makes the Jak/STAT signaling pathway regulates PD-L1 in cancer cells." (PMID 32986357, 2020). "We show that fibroblast-derived CXCL9/10 promote lung colonization by directly stimulating growth of CXCR3+ cancer cells." (PMID 32198421, 2020). "One is that the discrepancy between the studies is because the role of CXCL10 / CXCL9 varies between different cancer disease." (PMID 32547545, 2020). "CXCR3 has been identified as a crucial receptor for NK chemotaxis in response to cancer-secreted ligands, CXCL9, CXCL10, and CXCL11." (PMID 32546200, 2020). "Similar to CXCL10, CXCL9 is one of the most extensively studied CXCR3 chemokines in cancer and also plays a dual role in the TME." (PMID 31216755, 2019). "Most members of the chemokine family, including CXCL1, CXCL2, CXCL5, CXCL9, CXCL10 and CXCL13, where they are secreted by cancer or stromal cells, such as cancer-associated fibroblasts (CAFs) and dendritic cells (DCs)." (PMID 30925930, 2019).
cancer (continued). "The immune‐related chemokine CXCL9 was the sixth signature protein, and it is increased in many cancers." (PMID 30019538, 2018). "A study directly supporting the idea that the activity of heterocomplexes can be relevant also in cancer was performed in our laboratory, showing the role of the CXCL9/CXCL12 heterocomplex in primary central nervous system lymphoma (PCNSL)." (PMID 30319638, 2018). "Of these six genes, we found four to be significantly correlated with CTL levels across nearly all cancer lineages: CXCL9, CXCL10, CCL5, and IL16." (PMID 29615613, 2018). "Detailed researches on the functions of CXCL12‐CXCR4/CXCR7 pathways and their cross‐talks with CXCR3, CXCL11, CXCL10, and CXCL9 remain urgently warranted, which help lead to safer and more efficient use of their molecular inhibitors in targeted cancer therapy." (PMID 28544785, 2017). "In summary, chemokine CXCL9 was found to facilitate the metastasis ability of HCC CD133+ cancer cells, and CXCR3 receptor subtype CXCR3-A was found to play a key role during the metastasis, which was studied in this current study." (PMID 26883105, 2016). "Here, the role of CXCL9 in cancer development was reviewed, as well as the molecular mechanisms leading to aberrant expression of CXCL9 in cancer and the potential clinical applications of CXCL9 in diagnosis, prognosis, and cancer treatment." (PMID 27726306, 2016). "For instance, CXCL9, CXCL12, PDGF-BB, and VEGF, all of which are well-known factors associated with cancer cell invasion, were also detected by the cytokine antibody array in this study." (PMID 25271422, 2014). "Regarding effects on cell growth, CXCL9 has been shown to inhibit intestinal cell proliferation and also to have antitumor activity in a murine cancer model." (PMID 24296981, 2014). "The serum concentration of CXCL9 was higher in cancer patients (mean: 851, min: 121, max: 3941 pg ml−1) compared with normal volunteers (mean: 635, min: 12, max: 4327 pg ml−1) (P=0.013)." (PMID 20068563, 2010). "This complex behavior currently makes CXCL9 a controversial target in cancer therapy." (PMID 40362215, 2025). "CXCL9 is documented as a favorable prognostic marker in several cancers, including CRC." (PMID 40168086, 2025). "While it is apparent that the CXCR3/CXCL9 axis is important in cancer, it may depend on the target cell if the interaction has a progressive or inhibitory effect on the cancer cell." (PMID 40362215, 2025). "The CXCL9+ macrophage represents a newly defined macrophage subset characterized by superior immune activation capacity and indicates a favorable prognosis in various cancers." (PMID 41321309, 2025). "Interestingly, lamin-deficient cancer cells were found to present higher expression levels of many inflammatory chemokines such as CCL2, CCL9, CCL22, CXCL9, and CXCL10." (PMID 40708945, 2025). "CXCL9 is one of several cytokines that can activate the CXCR3 receptor within the DRG and has recently been implicated in the modulation of neuropathic pain in male rodents and cancer-related pain in female rodents." (PMID 38673862, 2024). "In contrast, CCL5 and CXCL9 expression in Pa and LM4 cancer cells was compared at the mRNA level to confirm whether CCL5 and CXCL9 are secreted by cancer cells in vitro." (PMID 39126553, 2024). "What may explain the association between CXCL9 and CXCL10 expression and cancer prognosis, as well as the response to ICT?" (PMID 39474427, 2024). "- CXCL9 rises in cancer as individuals age.- Targeting CXCL9 might mitigate the age-related decline of the vascular system and other physiological systems." (PMID 38590525, 2024). "Furthermore, in a meta-analysis of over one thousand cancer patients with seven different types of cancer, CXCL9 expression was one of the strongest predictors to ICB response." (PMID 37830618, 2023). "Also, RNAseq of cancer cells recovered from untreated tumors revealed elevated levels of CXCL9 and 10 in EA2 tumors, and higher levels of CXCL1 and 2 in EA1 tumors." (PMID 36739466, 2023).
cancer (continued). "The mechanism of inhibition of residual cancer was dependent on the CXCL9 axis." (PMID 37046739, 2023). "Research suggests that mutations in ASTE1 are induced by the Epstein–Barr virus in gastric mucosal cells, leading to the autonomous expression of CXCL9 by cancer cells through the NF-κB pathway, increasing IFN-γ in the microenvironment and stimulating immune response." (PMID 37664112, 2023). "Moreover, the upregulation of Cxcl9/10/11 in MC1R-depleted cancer cells resulted in significantly higher levels of Cxcl9/10/11 in the bulk MC1R-depleted tumors." (PMID 37714844, 2023). "Immunohistochemistry showed that three core proteins associated with the CXCR3 pathway, CXCR3, CXCL9, CXCL10, and were more highly expressed in cancer tissues from the immunotherapy-responder group than in tissues from the immunotherapy non-responder group (n = 1 per group)." (PMID 35562800, 2022). "CCL5 is expressed by cancer cells and CXCL9 is produced by immune cells in cancer tissue." (PMID 36618371, 2022). "Besides being a feasible predictive biomarker, CXCL9-inducing agents thus represent attractive combination partners to improve ICB in this cancer entity." (PMID 35314795, 2022). "Moreover, the use of romidepsin, an HDAC inhibitor, or celecoxib, a COX2 inhibitor, reinforces the expression of chemokines such as CXCL9/10 or CCL5 in cancer cells, macrophages and T cells." (PMID 36429101, 2022). "CXCL9 can be innate immune checkpoint for cancer immunotherapy." (PMID 35052427, 2021). "Previous reports suggested that anti-cancer drugs such as cisplatin and hydroxyurea induced mRNA expression of CXCL9/10/11 through cell cycle-specific DNA damage in human cancer cells, and the DNA topoisomerase I inhibitor, irinotecan, is also known to cause cell cycle-specific DNA damage." (PMID 34413454, 2021). "The role of CXCL9 play in human cancers remains ambiguous and contradictory." (PMID 34367961, 2021). "CXCL9 was the only independent prognostic factor for cancer-specific survival." (PMID 34501934, 2021). "Importantly, CXCL10 and CXCL9 are highly expressed by human cancer cells, and this expression is correlated with a good prognosis." (PMID 34944943, 2021). "Additionally, Gzmb, an effector molecule involved in CD8+ killing of cancer cells, and Cxcl9, a chemokine important to CD8+ recruitment, were both highly elevated in the tumors of Pik3cg−/− mice compared to WT mice." (PMID 33668795, 2021). "CXCL9 which may also be pro-tumorigenic, is upregulated during BCa therapy and participates in augmenting the response to cancer therapy with checkpoint blockade." (PMID 33946495, 2021). "In addition, TGF-β together with some chemokines and cytokines such as IL-6 and CXCL9 promote cancer progression by suppressing the antitumor immune response leading to the disruption of T cell function and cancer cell immune evasion." (PMID 33027902, 2020). "In addition to the increased ability of CXCR3+ cancer cells to induce Cxcl9/10 expression in lung fibroblasts, this subpopulation of cancer cells is also likely to benefit from this crosstalk." (PMID 32198421, 2020). "We therefore reasoned that CXCR3+ cancer cells may secrete higher levels of IL-1α/β, in turn leading to elevated production of CXCL9/10 in fibroblasts." (PMID 32198421, 2020). "Moreover, intravenous injection of CXCL9/10-expressing MDA or SUM cancer cells resulted in enhanced metastatic colonization as compared with the respective control cells." (PMID 32198421, 2020). "In addition, the levels of FGFBP1, DCN, FUR, and CXCL9 differed significantly between the benign and cancer groups by univariate analysis (ANOVA)." (PMID 30019538, 2018). "Moreover, CXCL11 was further down-regulated in liver metastases as compared to matched primary tumors, and above-threshold expression of CXCL9 and CXCL11 was significantly associated with longer cancer-specific and recurrence-free survival." (PMID 29163806, 2017).
cancer (continued). "Similarly, treatment of Caski and CSCC1 cancer cells with entinostat resulted in a higher production of CCL2, IL-8 and CXCL9 by the cancer cells when stimulated with IFN-γ and TNF-α than dimethylsulphoxide carrier control-treated cells." (PMID 26055519, 2015). "Moreover, we identified a cytokine, CXCL9, which is likely regulated by exercise and may have a direct effect on cancer cell growth." (PMID 40362215, 2025). "Hence, the downregulated expression of Cxcl9/10/11 is more likely related to the inhibition of cancer cell proliferation and other soluble factors in the microenvironment may be involved in the accumulation of antitumor cells in ascites." (PMID 40105652, 2025). "Moreover, high CXCL9 expression predicted better OS in the TCGA pan‐cancer cohort (p < 0.001)." (PMID 38434763, 2024). "Likewise, IFNγ–CXCL9/10/11–CXCR3 axis is significant for cancer immunity." (PMID 38786066, 2024). "In contrast, the expression of genes regulating immune cell trafficking (e.g., CXCL13, CXCL9, XCL2, CCL5), T-cell activation and clonal expansion (e.g., CD27, CD28, ICOS, IL21, IL2) were massively decreased in 9p21-loss tumors across multiple cancer types/subtypes." (PMID 34556668, 2021). "However, it is unclear how CXCL9-induced evasion of cancer cells from host immunosurveillance." (PMID 33407095, 2021). "Our data, revealing that CXCL9/10 are selectively induced in fibroblasts by highly metastatic cancer cells in early metastasis, suggest that these chemokines may confer a crucial metastatic advantage to cancer cells." (PMID 32198421, 2020). "In addition to these chemokine receptors, chemokine ligands such as CXCL1, CXCL2, CXCL5, CXCL6, CXCL8, and CXCL9 have been also significantly correlated with poor survival and metastasis in several cancers by recruiting MDSCs and suppressing the antitumoral activity of CD8+ T effectors cells." (PMID 32719800, 2020). "Furthermore, levels of DCN and CXCL9 also differed between cancer subtypes." (PMID 30019538, 2018). "Interestingly, we observed not only an overall increase in CXCL9 in cancer, but also a significant increase in ER‐negative subtypes compared to luminal A cancers, and these levels correlated significantly with levels of the TIL‐related markers CD8A, CD4, and CD5." (PMID 30019538, 2018). "This study suggests that Fibronectin 1/CXCL9 dosage in serum could screen a significant rate of BC, including ER-negative, and that differential gene expression analysis is a good approach to select candidate biomarkers to set up blood assays cancer screening." (PMID 20068563, 2010). "The same NRF2 activation gradient separates pro-inflammatory CXCL9+ and anti-inflammatory SPP1+TAMs across diverse human cancers." (PMID 41176316, 2025). "In PTC, IFN-γ stimulates the release of chemokines, notably CXCL9 and CXCL11, which exert antiproliferative effects on PTC cells and restrict cancer cell migration." (PMID 40150133, 2025). "CXCL9, CXCL10, and CXCL11 are selective ligands for the C‐X‐C motif chemokine receptor 3 (CXCR3) and are secreted by cancer cells." (PMID 40105652, 2025). "Baseline expression levels of CXCL9, CXCL10, and CXCL11 were relatively low and comparable between MTAP-WT and MTAP-KO CL1–0 and 786–0 cancer cells, as well as between CL1–5 Mock and MTAP-expressing cells." (PMID 41246302, 2025). "Upregulation of these genes was confirmed by qPCR, and ELISA demonstrated that secretion of CXCL9 and CXCL10 was strongly increased in cancer cells co-treated with TAK-243 and IFN-γ." (PMID 39540840, 2025). "Intriguingly, apart from the T cell chemokines CXCL9 and CXCL10, we observed upregulation of surface MHC-I expression upon UBA1 inhibition or depletion in various cancer models." (PMID 39540840, 2025). "Previous studies have established the potentially opposing roles of CXCL9 and SPP1 in cancer biology." (PMID 40936719, 2025).